IL6 (interleukin 6)
Diseases named in the same sentence as IL6 in open-access papers (continued):
Sharing a sentence is not in itself a finding about the gene and the disease.
breast cancer (continued). "Of the cytokines participating in the cancer process, interleukin 6 (IL-6) has been shown to promote breast cancer metastasis, and high IL-6 levels are associated with poor clinical outcomes in breast tumors." (PMID 26512918, 2015). "IL-6 has previously been shown to upregulate cathepsin B, a protease associated with breast cancer progression." (PMID 26268945, 2015). "Excessive IL-6 has been demonstrated in primary breast tumors and breast cancer patient sera and is associated with poor clinical outcomes in breast cancer." (PMID 25881039, 2015). "Previous research has shown that IL-6 and IL-8 are associated with the invasiveness of breast cancer cells." (PMID 25691060, 2015). "Another study done by Mills and his Colleagues (2008) 21 demonstrated that 3 cycles of chemotherapy for breast cancer lead to elevations in inflammatory markers including IL-6, associated with endothelial and platelets activation." (PMID 25225536, 2014). "In breast cancer, high levels of the inflammatory cytokine interleukin-6 (IL-6) have been associated with disease-free survival and treatment resistance." (PMID 25305747, 2014). "In breast cancer patients, a high level of the inflammatory cytokine interleukin-6 (IL-6) has been associated with increased tumour stage, lymph node infiltration, recurrence, and treatment resistance." (PMID 25305747, 2014). "The common G allele of the rs1800795 IL-6 promoter variant showed association with unfavorable survival outcomes of patients with ovarian cancer, breast cancer, neuroblastoma and hematologic malignancies." (PMID 24886605, 2014). "The well-studied SNP rs1800795/-174 G > C that is located in the promoter region of IL6 has been associated with fatigue and survival among breast cancer patients, and the effects of this SNP appear to vary according to tumour ER-status." (PMID 25305747, 2014). "Studies of the association between IL6 genotype and breast cancer prognosis in other ethnic groups are warranted." (PMID 25305747, 2014). "Several IL6 single nucleotide polymorphisms (SNPs) have been associated with breast cancer risk and prognosis." (PMID 25305747, 2014). "This translational study investigated the association between IL6 genotypes, ER-status, and treatment on the risk of early events among breast cancer patients." (PMID 25305747, 2014). "They suggested that the variants of ERCC2, TLR4, IL-2, IL-6, and IL-21 genes had associations with breast cancer prognosis respectively." (PMID 25075970, 2014). "In patients with breast cancer, IL-6 is associated with a poor prognosis because the levels increase in advanced stages and are associated with a higher number of metastases." (PMID 23552194, 2013). "Clinical studies have shown elevated IL-6 levels in breast cancer to be associated with poor breast cancer prognosis and to increase with tumor grade and number of metastatic sites." (PMID 23175106, 2013). "IL6 over-expression has been implicated in the tumourigenesis of multiple myeloma, ovarian, renal cell, prostate, cervical and breast carcinomas." (PMID 23874655, 2013). "The increased production of IL-6 from cancer-associated adipocytes promotes breast cancer cell invasion." (PMID 22482060, 2012). "An IL-6 gene expression pattern induced by heterotypic interaction of breast cancer cells with osteoblasts in vitro is associated with a higher rate of bone metastasis in vivo." (PMID 22235336, 2012). "IL-6 is elevated in human breast tumors and breast cancer patient sera, and is associated with a poor prognosis in breast cancer." (PMID 22134360, 2012). "Our region on chromosome 7 contains the AHR gene that has been associated with breast cancer risk, and IL6, which contains a marker associated with increased risk for breast carcinoma." (PMID 23190577, 2012). "Independent studies have shown that IL-6 is associated with a poor prognosis in breast cancer and is capable of supporting tumour growth in stromal-dependent mechanisms." (PMID 22075946, 2011).
breast cancer (continued). "MCF7 metastatic breast cancer cells have been shown to constitutively express IL-6, which is associated with increased expression of Snail1 and Twist1, and exhibit an EMT phenotype." (PMID 21647291, 2011). "Interleukin-6 (IL-6) was found to cause multidrug resistance in breast cancer cells by activating the CCAAT enhancer-binding protein family of transcription factors and inducing mdr1 gene expression." (PMID 21931812, 2011). "IL-6 has also been implicated in the induction of the breast cancer cell EMT phenotype, and recent reports suggest the role of TG2 in the EMT phenomena of both breast and ovarian cancer cells." (PMID 21967801, 2011). "Considering the close relationship existing between mammospheres and CSCs, these findings support the very recent observation that IL-6 driven epigenetic changes are associated with CSCs features in breast cancer cells." (PMID 21092249, 2010). "Increased serum levels of the inflammatory cytokines IL-6 and IL-8 have been associated with poor prognosis in women with breast cancer." (PMID 18474099, 2008). "IL-6 can enhance motility of breast cancer cells and autocrine production of IL-6 causes multidrug resistance in breast cancer cells." (PMID 18939993, 2008). "The circulating level of interleukin 6 is thought to be elevated in the development and progression of many tumours including breast cancer and its up-regulation is associated with invasiveness and increased metastatic potential of ER negative tumours." (PMID 16842617, 2006). "We conclude that the −174 C allele of IL-6 is associated with a more aggressive breast cancer phenotype." (PMID 14735187, 2004). "In contrast, however, high levels of IL-6 protein and mRNA expression within the breast carcinoma tissue have been linked to better prognosis and to a less malignant phenotype." (PMID 14735187, 2004). "Serum and tissue levels of interleukin-6 (IL-6) have been implicated in the biological phenotype of breast carcinoma." (PMID 14735187, 2004). "In breast cancer, elevated serum interleukin‐6 (IL‐6) level is associated with a poor prognosis during eribulin treatment; however, the mechanisms underlying IL‐6‐mediated resistance and its potential as a therapeutic target remain unclear." (PMID 41189442, 2025). "Moreover, a recent systematic review analyzing 15 studies in breast cancer patients receiving chemotherapy reported that IL-6, IL-1β, and TNF-α were associated with varying degrees of cognitive impairment." (PMID 41155372, 2025). "Likewise, a recent study found that elderly breast cancer survivors scored inferiorly long-term neurocognitively than controls; higher IL-6 levels partially explained this association." (PMID 40584290, 2025). "Some scholars have also suggested that excessive sleep may lead to elevated levels of systemic inflammation and an increase in some inflammatory biomarkers, such as CRP and IL-6, which may predispose individuals to breast cancer." (PMID 40735026, 2025).
breast cancer (continued). "Whether IL‐6 dependency is intrinsically linked to breast cancer subtype remains uncertain, warranting further investigation." (PMID 41189442, 2025). "Previous research has indicated that elevated levels of IL-6 are related to the occurrence and progression of various cancers, including colorectal cancer, breast cancer, and ovarian cancer, and decreasing IL-6 might contribute to reducing the risk of cancer." (PMID 40817754, 2025). "Similarly, another RCT among breast cancer survivors found that reductions in IL-6 concentrations were associated with increased total hours of moderate- or high-intensity AE." (PMID 40895542, 2025). "Notably, IL-6 emerged as a robust prognostic factor: a high IL-6 level roughly doubles the risk of death or recurrence in breast cancer patients." (PMID 41007766, 2025). "In this study, we exploit two signaling pathways frequently hyperactivated in breast cancer, truncated glioma-associated oncogene homolog 1 (tGLI1) and interleukin-6/interleukin-6 receptor/glycoprotein 130 (IL-6/IL-6R/GP130) signaling, to directly target HER2-enriched breast cancer and TNBC." (PMID 39768178, 2024). "Other investigators discovered associations of high serum IL-6 levels with poor response to therapy, including resistance to chemotherapy and endocrine therapy, providing the rationale for combination treatment of breast cancer therapy with Ruxolitinib." (PMID 38339245, 2024). "With regard to functional characteristic, G/C and G/G genotypes (both associated with ‘high’ gene expression of IL-6) were significantly associated with the pathogenesis of Parkinson’s disease and reduced disease-free survival of breast carcinoma, respectively." (PMID 38927668, 2024). "We acquired data regarding C-reactive protein (CRP), interleukin (IL)-1a, IL-1b, and IL-6 expression and BC related to single nucleotide polymorphisms (SNPs) from two larger consortia (the genome-wide association studies and the Breast Cancer Association Consortium)." (PMID 38263420, 2024). "There was little evidence of an effect of cytokines, including TNFα and IL6, on breast cancer risk." (PMID 36867866, 2023). "It was revealed that T2DM individuals with CC genotype of IL-6 rs1800796 or GG genotype of HSPD1 rs2605039 were strongly associated with increased risk of breast cancer (OR (95%CI): 2.53 (1.45, 4.41) and OR (95%CI): 6.40 (2.29, 17.87), respectively) compared to non-T2DM individuals." (PMID 37510134, 2023). "The IL6/STAT3 pathway is aberrantly hyperactivated in breast cancer, is linked to poor prognosis in patients, and may drive mammary tumorigenesis in SI rats." (PMID 36980301, 2023). "Moreover, IL-8 and IL-6 have been associated with increased invasiveness metastatic potential and cancer recurrence in breast cancer cells." (PMID 37296927, 2023). "IL-6 can increase resistance of breast cancer cells to drug treatment by inducing Mdr1 gene expression, and downregulation of IL-6 is associated with better response to breast cancer treatment." (PMID 37880751, 2023). "In a cohort of 63 patient-derived scaffold cultures cultured with breast cancer cells, we observed significant correlations between IL-6 and progranulin secretion, clearly validating the association between IL-6 and progranulin also in human-based microenvironments." (PMID 38136303, 2023). "Therefore, this study aimed to clarify the underlying molecular mechanism of IL-6-regulated KDM2A in enhancing chemoresistance in breast cancer." (PMID 37821959, 2023). "Moreover, in breast cancer, a poor response to radiotherapy was associated with IL-6 and p-STAT3 expression." (PMID 36635302, 2023). "Down-regulation of IL-6 is linked to a better response to breast cancer treatment and a recent study showed that the IL-6R neutralizing antibody, tocilizumab, abrogated IL-6 signaling in breast cancer." (PMID 36835413, 2023).
breast cancer (continued). "In a study of the breast cancer population (Knüpfer and Preiss, 2007), IL-6, as a key inflammatory factor, plays an important role in promoting tumor progression, and high circulating levels of IL-6 and age are associated with poor prognosis in breast cancer patients." (PMID 37251343, 2023). "Moreover, we revealed that tumour-associated macrophages (TAMs) increase DNMT1 expression in breast cancer cells via the IL-6-pSTAT3-ZEB1-DNMT1 axis in the tumour microenvironment." (PMID 36273188, 2022). "In addition, IL-6 derived from cancer-associated adipocytes induced breast cancer invasion and metastasis by propagating cancer stem cell expansion." (PMID 35743249, 2022). "Meanwhile, IL-6 produced by infiltrating macrophages, cancer associated fibroblasts, and other immune cells, is a recognized potent driver of tumor growth and metastatic progression across many solid malignancies, including breast cancer." (PMID 35565421, 2022). "Studies have predicted the association of three IL-6 promoter polymorphisms (rs1800795, rs1800796, rs1800797) with increased risk of cervical cancer, colorectal cancer, breast cancer, prostate cancer, lung cancer, glioma, non-Hodgkin’s lymphoma, and Hodgkin’s lymphoma." (PMID 36215278, 2022). "For example, in a prospective study included 240 patients who underwent surgery for management of newly diagnosed breast cancer, the associations between plasma concentration of IL-6 and breast cancer recurrence during a six-year follow-up period were examined." (PMID 35924148, 2022). "Clinical studies have been reported IL6 protein as a regulator that associate with many types of cancers such as multiple myeloma, non‒small cell lung adenocarcinoma, prostate cancer, colorectal cancer, renal cell carcinoma, breast cancer, and ovarian cancer." (PMID 35399006, 2022). "IL-6 expression is associated with poor prognosis for breast cancer." (PMID 35924148, 2022). "In addition to the critical roles of IL-6/JAK/STAT3 signaling in breast cancer, hyperactivation of this pathway has also been implicated in suppressing anti-tumor immune responses in tumor microenvironment." (PMID 35924148, 2022). "The IL-6 signaling pathway is associated with tumor angiogenesis, and previous studies have found that the suppression of IL-6 signaling led to suppression of angiogenesis and migration of breast cancer." (PMID 35927985, 2022). "Overall, the data suggest that TAMs may be associated with IL-6 production in clinical settings of breast cancer." (PMID 35300689, 2022). "Therefore, it can be argued that even if ER+ breast cancer cells express low levels of IL-6, these cells can be highly susceptible to the presence of this cytokine in the microenvironment." (PMID 35163731, 2022). "We determined the effects of 12-weeks supervised exercise training on the frequency of T-cell subtypes in peripheral blood and their relationships with circulating levels of the muscle-derived cytokines (i.e. ‘myokines’) IL-6, IL-7, IL-15 and osteonectin in older women at high risk of breast cancer." (PMID 35321743, 2022). "In addition to being linked to fatigue, IL-6 has been shown to predict survival in patients with breast cancer." (PMID 35935260, 2022). "Indeed, high levels of IL-6 and IL-8 are associated with breast cancer recurrence only among patients with HER2 tumors." (PMID 34445170, 2021). "The promoter polymorphism IL-6 may underlie the positive correlation of IL-6 with ER– breast cancer." (PMID 35008370, 2021). "Patients with HER2+ breast cancer at risk for primary trastuzumab resistance could potentially be identified on the basis of a high-risk IL-6 promoter genotype, and future studies could be aimed at overcoming this resistance by inhibiting the IL-6 pathway." (PMID 33483516, 2021). "We investigated whether the mRNA expression of resistin, TNF- α, IL-6, IL-8, and ER-α in PBMCs are associated with breast cancer." (PMID 33517609, 2021).
breast cancer (continued). "Based on the ROC curve analysis the diagnostic performance of IL-6 was significant (0.825, 95% CI: 0.549-0.94, p = 0.030), thus, it might be considered as a breast cancer biomarker that reflecting an early and inflammatory stage of the disease." (PMID 33517609, 2021). "It was reported that high expression of both IL-6 and IL-8 are critical for the growth of TNBCs, and upregulation of proinflammatory cytokines, including IL-6 and IL-8, in serum is associated with a low survival rate and poor prognosis in breast cancer patients." (PMID 34680349, 2021). "Moreover, the expression of IL-1β, IL-6, IL-8 or IL-11 in breast cancer cells has been associated with their metastatic potential and aggressive behavior." (PMID 33809315, 2021). "The association between resistin, TNF-α, IL-6, IL-8, and ER-α expression and breast cancer." (PMID 33517609, 2021). "Moreover, preclinical studies have demonstrated that IL-6 is associated with the severity of various cancer types, such as breast cancer and pancreatic cancer." (PMID 34001144, 2021). "While there are multiple inflammatory pathways and molecules that have been implicated in ER+ breast cancer recurrence, the inflammatory cytokine interleukin-6 (IL-6) and its associated pathway has been shown to be associated with poor outcomes in ER+ breast cancer." (PMID 33483516, 2021). "This approach may allow us to elucidate an empirical pathway through which a substantial proportion of the susceptibility of GWA SNPs in CRP and IL-6 influences breast cancer risk through interactions with specific lifestyles." (PMID 33441805, 2021). "However, the presence of a high-risk IL-6 promoter genotype was significantly associated with increased risk of relapsed breast cancer in a univariate conditional logistic regression model (OR 2.35, 95% CI 1.16–4.77, p = 0.018)." (PMID 33483516, 2021). "The blood cancer, breast cancer, colon cancer, lung cancer, neuroblastoma, oral cancer, skin cancer, stomach cancer, thyroid cancer, ovarian cancer and pancreatic cancer showed insignificant associations with the IL-6 -174G/C polymorphism." (PMID 33684135, 2021). "Besides, increased expression of IL-6 has been found in a variety of tumors, such as lung cancer, gastric cancer, breast cancer and lymphoma, and is associated with poor clinical prognosis, which is consistent with our results." (PMID 34165442, 2021). "This suggests that FER rs10447248 may predispose breast cancer by inducing NF-κβ and IL-6 to trigger downstream signaling pathways." (PMID 34367982, 2021). "In addition, clinical studies have showed that both high levels of IL-6 or IL-8 have been associated with breast cancer recurrence." (PMID 33114046, 2020). "Blocking IL-6 and/or its receptor could be a trigger point to cure tumors associated with high levels of this cytokine, as in breast cancer." (PMID 32847008, 2020). "Also, Coulson associated the inhibition of progression with reduction of mammary tumor cell proliferation and of pSTAT3, TNFα and IL-6 in Losartan-treated group compared to control group." (PMID 32850009, 2020). "This positive association may be explained through the involvement of IL-6 in breast cancer cell migration and invasion by the activation of many factors, including estrogen." (PMID 33202561, 2020). "Recent findings from a phase I clinical trial of patients with breast cancer treated with atezolizumab (anti-PD-L1) indicate that elevated baseline plasma levels of interleukin 6 (IL-6) and C-reactive protein (CRP) are associated with reduced progression free and overall survival." (PMID 33123173, 2020). "It has been revealed that IL-6 levels are significantly elevated in lung and breast cancer patients associated with poor prognosis; moreover, IL-6 can affect all aspects of the tumorigenesis process by regulating proliferation, apoptosis, metabolism, survival, angiogenesis, and metastasis." (PMID 32847008, 2020).